INS (insulin)
Diseases named in the same sentence as INS in open-access papers (continued):
Sharing a sentence is not in itself a finding about the gene and the disease.
diabetes (continued). "Diabetes mellitus is a disease characterized by high blood glucose, caused by insufficient secretion of insulin relative to insulin requirements." (PMID 36099294, 2022). "The obvious treatments to counter hyperglycaemia involve reduction of blood glucose by the administration of therapeutic insulin or other medication that reduces circulating glucose levels (American Diabetes Association., 2020)." (PMID 35237171, 2022). "At the time of the study, which was at 14 weeks, insulin therapy partially rescued the diabetes-associated weight loss observed in untreated diabetic rats." (PMID 35574440, 2022). "Diabetes can be predicted using TGs and is related to an increased risk of diabetes, which decreases after insulin action and increases in the case of insulin resistance." (PMID 35673359, 2022). "Type 1 diabetes mellitus is an impairment of insulin secretion caused by autoimmune destruction of Langerhans β islets of the pancreas." (PMID 36091019, 2022). "Diabetes mellitus (diabetes, DM) is a metabolic disorder caused by decreased insulin levels due to autoimmune β-cell destruction (T1D) and/or insulin resistance (T2D)." (PMID 36433141, 2022). "Triggers for diabetes mellitus include genetic predisposition, infections generating states of insulin resistance in insulin receptors, increasing cortisol, insulin-resistant drugs (i.e., corticoids and progestogens), obesity, and pancreatitis." (PMID 35993079, 2022). "Patients who received only insulin therapy had a 3.91-fold higher risk of developing diabetes than those who received both insulin and tablet medication (HR=3.91, 95%CI: 1.36, 7.94)." (PMID 36262700, 2022). "In this study, we subjected Tg2576 mice to STZ to produce combined insulin-deficient diabetes and AD." (PMID 35701718, 2022). "The two main types of diabetes are caused by the pancreas failing to secrete enough insulin (type 1), or when body cells inappropriately respond to insulin (type 2)." (PMID 36005005, 2022). "Diabetes mellitus is a metabolic disorder linked to aberrant glucose concentration in the plasma and leads to insulin deficiency and/or impaired insulin activity." (PMID 35190649, 2022). "Hypoglycaemia is a common and potentially life-threatening condition in people with diabetes, commonly caused by medications such as insulin." (PMID 35340578, 2022). "A favorable prognosis is presented for a permanent neonatal diabetes mellitus (PNDM) patient with a novel mutation in the INS gene in China." (PMID 36686471, 2022). "Diabetes mellitus is a chronic metabolic disorder characterized by alteration in carbohydrate metabolism that is associated with reduction in insulin secretion or its action by which blood glucose level increases." (PMID 35831936, 2022). "Whereas a male aged 55 years with one year duration of diabetes and on insulin has an estimated 3-year risk of 8% to develop STDR." (PMID 35898318, 2022). "Understanding the current disposal practices for at-home insulin needles among patients with diabetes and identifying the factors associated with safe sharps disposal are essential for tailoring interventions to improve such practices in China." (PMID 36568796, 2022). "At present, T1DM is regulated using strict blood sugar control, exogenous insulin supplementation, dietary adjustment, appropriate exercise, and other physiological factors, among which insulin-replacement treatment is a cornerstone therapy for T1DM patients." (PMID 36686651, 2022). "Primary diabetic encephalopathy is caused by hyperglycemia and impaired insulin action, which develops depending on the duration of diabetes and is associated with apoptosis, loss of neurons, and decline in cognitive function." (PMID 36359305, 2022). "It has been established that in T2DM, β cells secrete sufficient insulin to meet the required functions caused by type 2 diabetes mellitus (T2DM)." (PMID 36188222, 2022). "Diabetes is defined by chronically elevated blood glucose levels caused by altered insulin metabolism." (PMID 36190648, 2022).
diabetes (continued). "Diabetes results in insufficient absolute insulin secretion, resulting in higher blood glucose and causing metabolic disorders and even damage to multiple systems." (PMID 36407115, 2022). "Diabetes, one of the most common metabolic diseases, results in hyperglycemic conditions caused by insufficient insulin secretion and reduced insulin sensitivity." (PMID 36618686, 2022). "In patients with diabetes with relatively steady levels of insulin, a rise in glucagon causes hyperglycemia and glycosuria." (PMID 35784565, 2022). "The report supported the advocation of higher intensity exercise regimens for improving insulin sensitivity, body composition and blood pressure, especially in those at risk of cardiovascular disease and diabetes." (PMID 35141057, 2022). "When pancreatic tissue is removed, the body releases less insulin, and the risk of developing diabetes mellitus is high." (PMID 35273837, 2022). "Other findings included a chronic low-grade inflammation in diabetes patients with decreased glucose tolerance, which was caused in part by IL-1β generated by glucose and further hindered insulin secretion." (PMID 35337139, 2022). "For example, UCP2 upregulation in islets of ob/ob mice caused reduced ATP synthesis and attenuated insulin release, ultimately developing obesity and type 2 diabetes mellitus." (PMID 36266633, 2022). "CA has been reported to have various biological effects such as antibacterial, antitumor, antimicrobial, and antioxidant, in addition to improving obesity, diabetes, hyperlipidemia, glucose intolerance, insulin secretion, and memory deficiency." (PMID 36015301, 2022). "Diabetes is defined by the loss of blood glucose homeostasis, due to the inadequate action of insulin, a hormone produced by the endocrine β-cells of the pancreas." (PMID 35769263, 2022). "The good news for type 2 DM patients is that if insulin, medication, weight loss, physical activity, and dietary changes result in normal blood glucose levels, their diabetes is well controlled, and their risk of developing diabetes is reduced." (PMID 35795845, 2022). "In the classical view, decreased insulin sensitivity caused by excess adipose tissue heralds the progression of metabolic disorders towards pre-diabetes (IFG, IGT) and then diabetes." (PMID 36589801, 2022). "Diabetes mellitus (DM) is a metabolic disease characterized by hyperglycemia, caused by insulin deficiency (type I) or decreased insulin sensitivity (type II)." (PMID 35966750, 2022). "It has been shown that the estrogen signaling pathway regulates rapid changes in systemic metabolism, fat distribution, and insulin action associated with diabetes." (PMID 35936218, 2022). "Diabetes is characterized by the loss or degradation of structural proteins exhibiting a severe loss in body weight caused by proteolysis and an insulin deficiency triggering a reduction in the protein content in the muscular tissue." (PMID 36080407, 2022). "We classified 6-year IR status [improved, unchanged (referent), worsened] using a 1-SD change in fasting insulin between visits and defined incident diabetes based on American Diabetes Association criteria." (PMID 36229451, 2022). "This concern is heightened for patients with insulin-requiring diabetes, many of whom are categorized as very high risk by the ADA risk index." (PMID 35634376, 2022). "Type 1 diabetes mellitus (T1D), previously known as insulin-dependent diabetes, is a chronic impairment in production or an absolute deficiency of insulin." (PMID 36091019, 2022). "Overall, age over 65 years, HR 3.27 [2.83, 3.77], p < .0001,58, 157, 172 HbA1C over 70 mmol, HR 2.75 [2.60, 2.91] p < .0001, insulin use HR 2.80 [2.29, 3.44], p < .0001, were found to increase the risk of mortality amongst patients with diabetes." (PMID 35441801, 2022). "The spectrum of diabetes-associated mutations in the insulin gene implicates diverse genotype-phenotype relationships." (PMID 35299958, 2022).
diabetes (continued). "Hyperglycaemia and insufficient release of insulin is characteristic for diabetes (American Diabetes Association., 2009)." (PMID 35237171, 2022). "A vigorous debate ensued during the 1960s and beyond regarding the relative importance of deficiencies in insulin release versus insulin action in the pathogenesis of diabetes." (PMID 35163746, 2022). "Of relevance, mitochondrial damage involving accumulated Pi was found in cultured pancreatic beta cells and islet cells, which is associated with reduced insulin biosynthesis and secretion, reactive oxygen species, and cell apoptosis in diabetes mellitus." (PMID 35897635, 2022). "The results showed that age, BMI, blood diastolic pressure, insulin, blood glucose, and skin thickness were the risk factors for diabetes recurrence." (PMID 35936376, 2022). "Diabetes mellitus (DM) is a complex metabolic disease characterized by blood hyperglycemia, attributable to a deficiency in insulin production or to a reduction in insulin uptake by peripheral cells." (PMID 36498923, 2022). "Management of diabetes is often mostly associated with insulin infusions, usage of specific electronic devices, and measuring blood glucose levels." (PMID 36687959, 2022). "Animal models of diabetes and cell lines will be beneficial in the search for factors associated with the formation of a defective plasma insulin pattern in diabetes, as well as in understanding the mechanisms involved." (PMID 35268696, 2022). "The initial insulin reduction affected diabetes risk: diabetes incidence was lowest among those with the greatest therapy-induced reduction." (PMID 36295635, 2022). "Diabetic Mellitus (DM) is marked by an elevated blood glucose level (hyperglycemia) and is caused by a deficiency in the body's ability, to synthesize or respond to insulin." (PMID 36387032, 2022). "Nicotine-induced immunosuppression is associated with preserved insulin content and reduced incidence of diabetes in type 1 diabetes-prone mice models." (PMID 35953788, 2022). "Diabetes is a common metabolic disease defined as the disorder of homeostatic control of blood sugar levels, which mainly caused by the insulin secretion deficiency resulting from the destruction of pancreatic β-cells." (PMID 35395037, 2022). "Almost three decades ago, protein particle formation was evaluated and associatedwith the presence of silicone oil (SO) in the insulin after analyzing a “cloudy”insulin formulation administrated with plastic syringes in patients withuncontrolled diabetes." (PMID 35857984, 2022). "The close association between diabetes mellitus and HF is a result of the detrimental effect of pivotal pathogenic factors: chronic glucotoxicity and lipotoxicity, as well as altered insulin signaling." (PMID 35329796, 2022). "Initiation of insulin is even more strongly associated with risk of PDAC, with a relative risk of 5.6, and 45% of PDAC cases with diabetes have been treated with insulin." (PMID 34728468, 2022). "According to its pathogenesis, it can be divided into diabetes mellitus (DM) type 1 (T1D) caused by insufficient insulin secretion and DM type 2 (T2D) caused by insulin resistance; both can lead to hyperglycemia in humans." (PMID 36364943, 2022). "Here the authors report a proof-of-concept study for small molecule SWELL1 modulators as a therapeutic approach to treat diabetes and associated liver steatosis by enhancing systemic insulin-sensitivity and insulin secretion in mice." (PMID 35145074, 2022). "Diabetes mellitus (DM) is a group of metabolic diseases characterized by chronic hyperglycemia caused by disorders of insulin secretion and/or utilization caused by multiple etiologies." (PMID 35270682, 2022). "Reduced body size is a hallmark of diabetes in Drosophila, because the insulin signaling pathway serves both insulin‐ and IGF‐like functions in flies." (PMID 35678366, 2022).
diabetes (continued). "Diabetes is a common chronic disease characterized by chronic hyperglycemia with carbohydrate, fat and protein metabolic disorders, which is caused by insulin secretion deficiency or insulin action deficiency." (PMID 35701587, 2022). "These groups exhibit different risks for metabolic disease, including type 2 diabetes, and it is of interest if there is a relationship between insulin degradation and diabetes risk." (PMID 35163746, 2022). "Factors like diabetes duration, obesity, body mass index, insulin treatment, and hypertension increased the risk of preparation failure." (PMID 35294636, 2022). "These rodent models display amyloid deposits of IAPPs and the development of impaired insulin secretion, β-cell loss, and diabetes." (PMID 35563231, 2022). "Classic studies found clinical improvement in patients affected by AIP associated with the administration of glucose and concomitant insulin secretion, or after hyperinsulinemia associated with diabetes." (PMID 36613492, 2022). "Diabetes mellitus is characterize by the deficiency and resistance to insulin, resulting in hyperglycemia, moreover obesity has a strong association with diabetes and insulin resistance." (PMID 36496432, 2022). "Type 1 diabetes mellitus (T1DM) is caused by a deficiency of insulin production, while type 2 diabetes mellitus (T2DM) is linked to insulin resistance." (PMID 36045953, 2022). "There is a range of technologies involved in diabetes management, including insulin pumps with associated cannulas, glucose meters and glucose sensors, from many different manufacturers and models." (PMID 35627851, 2022). "Diabetes mellitus (DM) is a class of metabolic disease with defective insulin secretion or when the body cannot utilize the insulin effectively, which is caused by two factors including both genetic and environmental factors." (PMID 36420273, 2022). "It seems to stabilize the insulin hexamers and insulin pancreatic storage, improve glycemia, and contrast diabetes-related risk factors." (PMID 35405968, 2022). "Increasing oxidative stress would play a role in diabetes progression, and chronic oxidative stress results in reduced responsiveness to insulin and ultimately causes diabetes." (PMID 35549705, 2022). "The development of diabetes can occur by the autoimmune destruction of beta cells, leading to a deficiency in insulin production, or by other factors that can result in tissue resistance to the action of insulin." (PMID 37746194, 2022). "ALA is a popular dietary supplement used in managing diabetes and obesity, as it reduces blood glucose levels, increases insulin sensitivity, and promotes weight loss." (PMID 35564468, 2022). "The disruption of insulin production associated with diabetes, in turn, disrupts the insulin signalling pathway which is a crucial part of the HSR system." (PMID 36032680, 2022). "Next, animals were subjected to an OGTT, a diagnostic tool for diabetes that reflects the body’s metabolic efficiency and insulin resistance." (PMID 36296987, 2022). "Increased blood glucose leads to producing more insulin by the pancreas and finally causes hyperinsulinemia and IR which can develop chronic diseases such as cancer, diabetes, and cardiovascular diseases." (PMID 36529727, 2022). "Diabetes mellitus is a metabolic disorder characterized by high blood glucose levels caused by insufficient or ineffective pancreatic insulin." (PMID 35770046, 2022). "Diabetes mellitus (DM) is one of the most important metabolic disorders associated with chronic hyperglycemia and occurs when the body cannot manage insulin secretion, insulin action, or both." (PMID 35711333, 2022). "Low monthly income, longer duration of diabetes, poor glucose control and being on Insulin treatment alone were found to be the most important risk factors associated with the development of DR in diabetes." (PMID 35061820, 2022).
diabetes (continued). "Insulin regulates the overall blood glucose concentration, and defects in insulin biogenesis and secretion are associated with the onset of diabetes and related diseases." (PMID 35562580, 2022). "Hypertension, together with reduced insulin sensitivity and dyslipidemia, can contribute to an increased cardiovascular risk in patients with diabetes." (PMID 35721726, 2022). "GLP-1RAs have been found to significantly reduce AF risk in patients with diabetes compared with placebo and other glucose-lowering agents including metformin, sulfonylureas, and insulin." (PMID 36380358, 2022). "Deficiencies in LPL play an important role in the pathophysiology of hyperlipidemia in diabetes and the treatment with insulin increases PLP activity thus causing a fall in plasma triglycerides." (PMID 35620400, 2022). "For instance, alpha-glucosidase inhibitors, which lower the glycemic response to carbohydrate, produce weight loss of ~1 kg, while also lowering HbA1c, in contrast to some other diabetes drugs (including insulin) that cause weight gain." (PMID 35896818, 2022). "Diabetes mellitus is a progressive and complex metabolic disorder, characterized by chronic hyperglycemia, caused by impaired insulin secretion and (or) utilization." (PMID 35409105, 2022). "The association between mtDNA-CN and insulin sensitivity remained, even after accounting for diabetes status (P = 0.007)." (PMID 35849594, 2022). "Insulin was shown mostly to prevent diabetes-associated LUT dysfunction as well as can reverse the symptoms." (PMID 35545721, 2022). "Subgroup analyses showed that intensive insulin regimens decreased the risk of SSIs in patients with diabetes, in cardiac and abdominal surgical procedures, and during the intraoperative and postoperative phases of surgery." (PMID 35402490, 2022). "Diabetes mellitus (DM) is a chronic hyperglycemic metabolic condition caused by decreased insulin production, peripheral insulin resistance, or both." (PMID 36440220, 2022). "In a model of diabetes, ferrostatin-1 reduces accumulation of lipid peroxides and infiltration of macrophage, and increases the number of insulin-associated cells, protecting islets from streptozotocin (STZ)-induced damage." (PMID 35874833, 2022). "The results indicated that diabetics utilizing insulin therapy had a higher risk of contracting COVID-19 than those without diabetes." (PMID 36579222, 2022). "Diabetes mellitus (DM) is described as having abnormal blood glucose levels caused by a defect in insulin secretion and/or insulin action." (PMID 35159487, 2022). "Hypoglycemia, a common adverse effect of treatment of diabetes mellitus with insulin and sulphonylureas, is associated with impairment of cognitive function, which can have significant consequences on everyday behavior." (PMID 35571045, 2022). "Signaling from the proton-activated cell-surface receptor TDAG8 was rewired into a cAMP-sensitive response element operated by CREB1 for the expression of transgenes, including insulin for the treatment of diabetes-associated ketoacidosis." (PMID 36225597, 2022). "In humans, endothelial dysfunction is linked with diabetes mellitus via a mechanism that interrupts intracellular signaling pathways of insulin and NO production." (PMID 35449082, 2022). "Low family monthly income, longer duration of diabetes, poor glucose control and being on insulin treatment alone were important risk factors of diabetic retinopathy." (PMID 35061820, 2022). "After adjustment for glucose tolerance and insulin sensitivity/secretion, high phosphate concentration is associated with future diabetes development." (PMID 36364739, 2022). "Diabetes mellitus (DM), which is usually characterized by an absolute or relative deficiency of serum insulin concentrations, is one of most serious metabolic diseases with a sharply increasing incidence globally." (PMID 35010985, 2021).